PRDX1 (peroxiredoxin 1)
Diseases named in the same sentence as PRDX1 in open-access papers (continued):
Sharing a sentence is not in itself a finding about the gene and the disease.
cervical carcinoma (continued). "This may be one of the mechanisms by which PRDX1 inhibits the apoptosis of tumor cells and participates in cervical cancer tumorigenesis." (PMID 31956363, 2020). "Besides, the impacts of PRDX1 expression on tumor cell proliferation, differentiation, and apoptosis have rarely been investigated in human cervical cancer." (PMID 31956363, 2020). "Although further studies are necessary to confirm our speculation, the stimulative effect of PRDX1 on cervical cancer cell migration and invasion is of particular interest." (PMID 31956363, 2020). "We hypothesized that PRDX1 regulated the process of cervical cancer cell proliferation via upregulating the expression of Nanog and PCNA." (PMID 31956363, 2020). "Moreover, PRDX1 overexpression increased invasion and migration of SiHa cervical cancer cells via up-regulating the expression of Snail and matrix metalloprotein 9 (MMP-9) and down-regulating the expression of E-cadherin." (PMID 31956363, 2020). "Taken together, our results suggest PRDX1 function as an oncogene and PRDX1-specific inhibitor may be a promising drug for target therapy in patients with cervical cancer." (PMID 31956363, 2020). "In addition, further study is needed to investigate the in vivo effect of PRDX1 expression on the metastasis of cervical cancer cells." (PMID 31956363, 2020). "Additionally, the expression of thioredoxin 1, peroxiredoxin 1 and peroxiredoxin 2 was significantly up-regulated in post-chemotherapy tissues compared to pre-chemotherapy cervical cancer tissues." (PMID 31470801, 2019). "Overexpression of PRDX1 significantly promoted proliferation and inhibited apoptosis by increasing the expression of Nanog, proliferating cell nuclear antigen (PCNA), B-cell lymphoma-2 (Bcl-2) and downregulating the expression of Bcl2-associated X protein (BAX) in SiHa cervical cancer cells." (PMID 31956363, 2020). "Next, whether PRDX1 was involved in cervical cancer cell apoptosis was examined." (PMID 31956363, 2020). "In this study, the lentiviral vector containing PRDX1-cDNA or PRDX1-shRNA was used to up-regulate or down-regulate the expression of PRDX1 in cervical cancer cells, and the functional roles of PRDX1 on the biological behavior of cervical cancer were investigated." (PMID 31956363, 2020). "However, the expression of PRDX1 in cervical cancer tissues is still unclear." (PMID 31956363, 2020). "The research demonstrates that PRDX1 and PRDX2 modulate apoptosis in cervical cancer cells through the PI3K/AKT pathway-mediated ER stress, facilitated by the clearance of ROS." (PMID 38821929, 2024). "The analysis revealed that, compared to normal tissues, PRDX1 and PRDX2 expression levels were significantly higher in cervical cancer tissues." (PMID 38821929, 2024). "The research results emphasize the pivotal roles of PRDX1 and PRDX2 in the treatment of cervical cancer using BLM." (PMID 38821929, 2024). "Consistent with the previous findings, levels of PRDX1 and PRDX2 were significantly higher in cervical cancer tissues in comparison to normal cervical tissues." (PMID 38821929, 2024). "The results above indicate that the expression levels of PRDX1 and PRDX2 are significantly elevated in both cervical cancer patients and cervical cancer tissues compared to normal levels." (PMID 38821929, 2024). "The study explored the significant roles of PRDX I and II (PRDX1 and PRDX2) in the context of BLM treatment in SiHa cervical cancer cells." (PMID 38821929, 2024). "Further investigation into the impact of PRDX1 and PRDX2 on the prognosis and survival of cervical cancer patients was conducted, including their expression levels at various stages of the disease." (PMID 38821929, 2024). "This part of the study aimed to further elucidate the roles of PRDX1 and PRDX2 in cervical cancer treatment." (PMID 38821929, 2024).
cervical carcinoma (continued). "In our previous study, we detected expression changes of proteins in cervical cancer tissues before and after neoadjuvant chemotherapy (NAC) by using mass spectrometry, and found that PRDX1 was significantly increased after NAC treatment." (PMID 31956363, 2020). "Additionally, the xenograft model was established to evaluate whether PRDX1 affects the growth of cervical cancer in vivo, and proliferation index and apoptosis index in tumor tissues were assessed by the TdT-mediated dUTP nick end labeling (TUNEL) assay and PCNA immunohistochemical staining." (PMID 31956363, 2020). "This suggests that targeting PRDX1 and PRDX2, possibly through the use of inhibitors, might amplify the anti-cancer efficacy of BLM in cervical cancer therapy." (PMID 38821929, 2024). "This suggests that modulating PRDX1 and PRDX2 expression could enhance BLM’s efficacy against cervical cancer." (PMID 38821929, 2024). "Moreover, the expression levels of PRDX1 and PRDX2 were consistently higher across different stages of cervical cancer." (PMID 38821929, 2024). "The expression of PRDX1 in 306 cervical cancer tissues was much higher than that in 13 noncancerous tissues." (PMID 31956363, 2020). "On account of the lack of understanding about the role that PRDX1 played in cervical cancer, further study should be carried out to elucidate its function." (PMID 31956363, 2020). "Materials and methods: The expression of PRDX1 in human cervical cancer tissues and adjacent non-tumor tissues were detected by immunohistochemistry (IHC)." (PMID 31956363, 2020). "The effects of PRDX1 overexpression on cervical cancer have not been investigated thoroughly." (PMID 31956363, 2020).
Stroke (11 papers, 2016 to 2025). Sudden impairment of blood flow to a part of the brain due to occlusion or rupture of an artery to the brain. "PRDX1 has been associated with redox protective mechanisms and is found at higher levels in the ischemic score, penumbra, and circulation in patients with stroke." (PMID 38420847, 2024). "Our methylation analysis further identified two PRDX1-related methylation sites (cg02631906 and cg08483560) that show a causal relationship with stroke risk, highlighting the epigenetic regulation of PRDX1." (PMID 39595569, 2024). "Collectively, these findings provide novel insights into the role of disulfidptosis and PRDX1 in stroke, offering new avenues for therapeutic intervention and underscoring the diagnostic and therapeutic potential of PRDX1 in ischemic stroke." (PMID 39595569, 2024). "Additionally, our immune infiltration analysis linked PRDX1 to key immune cells, underscoring its dual role in stroke progression and recovery." (PMID 39595569, 2024). "PRDX1 scavenges ROS in cells under oxidative stress and is required for the antioxidant function of stroke-associated microglia, which are specifically activated during stroke ischemia/reperfusion injury." (PMID 39796134, 2024). "Studies have shown the protective effects of Peroxiredoxin 1 (PRDX1) on stroke through disulfidptosis and the ischemic postconditioning’s (IPostC) mechanism." (PMID 40109666, 2025). "Despite this, PRDX1 was chosen for further analysis due to its critical role in the oxidative stress response, a key factor in stroke pathology." (PMID 39595569, 2024). "To gain insight into the role of PRDX1 in stroke and IPostC, we used the STRING website to predict 10 genes significantly associated with PRDX1 protein expression and show their interaction networks." (PMID 39595569, 2024). "Although the role of PRDX1 in ischemic stroke has been mentioned in other studies, our research provides fresh insights by identifying key genes and networks related to stroke, especially within the context of IpostC." (PMID 39595569, 2024). "Among these, PRDX1 emerged as a pivotal gene, playing a crucial role in the oxidative stress response during stroke." (PMID 39595569, 2024). "Recent research highlights the increased expression of Peroxiredoxin 1 (PRDX1) in stroke patients, suggesting its role in oxidative stress response and potential as a stroke biomarker." (PMID 39595569, 2024). "Understanding the temporal and contextual nuances of PRDX1’s actions is fundamental for developing stroke therapies that capitalize on its protective effects while minimizing inflammatory harm." (PMID 39595569, 2024). "Through bioinformatics analyses, including PCA, UMAP, and differential gene expression, we were able to differentiate the effects of stroke from those of postconditioning, identifying Peroxiredoxin 1 (PRDX1) as a key gene of interest." (PMID 39595569, 2024). "The discovery that IPostC inhibits PRDX1 is significant as it sheds light on a potential therapeutic mechanism for reducing stroke-induced brain injury." (PMID 39595569, 2024). "GSEA highlighted PRDX1’s involvement in protective pathways against ischemic damage, while its correlations with various proteins suggest a broad impact on stroke pathology." (PMID 39595569, 2024). "In conclusion, our study elucidates stroke’s molecular mechanisms, identifying key genes and their roles in disease progression, with a focus on PRDX1’s protective actions against stroke via disulfidptosis and IPostC mechanisms." (PMID 39595569, 2024). "Studies highlight PRDX1’s antioxidative defense mechanism in mitigating stroke damage, emphasizing its potential as a therapeutic target." (PMID 39595569, 2024). "One protective microglia subtype in stroke-associated microglia is characterized by the upregulation of an antioxidant enzyme, Peroxiredoxin-1 (Prdx1), which induces the expression of stroke-protective molecules, such as osteopontin and ferritin." (PMID 37229425, 2023).
Stroke (continued). "Circulating levels of PRDX1 are elevated in patients following acute stroke and a recent study highlighted PRDX1 as a biomarker of stroke onset early after stroke." (PMID 32733466, 2020). "Overall PRDX1 median levels were significantly higher in stroke patients than in the control population: 6.9 ± 13.7 vs. 3.5 ± 4.5 ng/mL (p < 0.01)." (PMID 27924073, 2016). "PRDX1 plasma levels in the stroke patients overall were significantly higher in samples withdrawn before 3 hours and before 6 hours than those withdrawn after these time intervals." (PMID 27924073, 2016). "PRDX1 levels were also higher from blood samples withdrawn before vs. after 3 hours following stroke onset, and before vs. after 6 hours." (PMID 27924073, 2016). "Additionally, we identified a shared causal variant (rs17522918) between PRDX1 and ischemic stroke, establishing a genetic link that supports PRDX1’s role in stroke pathology." (PMID 39595569, 2024). "The mechanisms behind PRDX1’s dual role in stroke-induced brain injury remain elusive." (PMID 39595569, 2024). "To elucidate the involvement of PRDX1 in stroke and ischemic postconditioning (IPostC), we utilized the STRING database to identify and visualize the interaction network of 10 genes closely associated with PRDX1 protein expression." (PMID 39595569, 2024). "Moreover, immune infiltration analysis suggested that PRDX1 influences both stroke progression and recovery, potentially impacting immune-related therapeutic strategies." (PMID 39595569, 2024). "PRDX1 is also significantly higher in stroke patients compared to control." (PMID 36909892, 2023). "In conclusion, this analysis of the kinetics of PRDX1, involved in oxidative stress during stroke, show that it could form the basis of a biologic method of estimating time of cerebral infarction." (PMID 27924073, 2016). "Median PRDX1 levels were significantly higher in stroke patients compared to controls." (PMID 27924073, 2016). "In the stroke patients, median PRDX1 levels were significantly higher in blood samples withdrawn before vs. after 3 hours following onset (11.7 ± 15.6 vs. 5 ± 11.6 ng/mL, p < 0.01) and in blood samples withdrawn before vs. after 6 hours following onset (9.6 ± 14.9 vs. 4.9 ± 11.9 ng/mL, p < 0.01)." (PMID 27924073, 2016). "The results of our study show that PRDX1 levels are high during the first hours following stroke onset suggesting that it could play a role in identifying patients with cerebral infarction who fall within the therapeutic window for reperfusion therapies." (PMID 27924073, 2016). "However, PRDX1 plays a dual role in stroke, involving both protective and damaging effects." (PMID 39595569, 2024). "Although a previous study reported that the circulating levels of the NRF2 target gene PRDX1 are almost doubled in stroke patients, we could not find any significant association in its levels and the risk of further events." (PMID 32733466, 2020). "The gene expression of PRDX1 and PRDX4 was elevated on day 7 in the hemisphere affected by stroke in comparison with the contralateral hemisphere and compared to day 3 (p < 0.05)." (PMID 40332314, 2025). "Conversely, research also reveals PRDX1’s damaging role in ischemic–reperfusion injury, promoting neuroinflammatory damage through the TLR4/NF-κB pathway and exacerbating stroke outcomes." (PMID 39595569, 2024). "In this study, four biomarkers, CDKN1A, GPX4, PRDX1, and PRDX6, were used to diagnose stroke and assess the treatment effects." (PMID 38360841, 2024). "NRF2 target genes include several antioxidant enzymes including PRDX1, thioredoxin 1 (TXN1), and heme oxygenase 1 (HMOX1) and its activation affords protection in animal models of stroke." (PMID 32733466, 2020). "We assessed the kinetics of peroxiredoxin 1 (PRDX1), a protein involved in oxidative stress during the acute phase of ischemia, and its ability to determine stroke onset in a population of patients with known onset of less than 24 hours and in a control group." (PMID 27924073, 2016).
Stroke (continued). "PRDX1’s correlation with these immune cells suggests its involvement in stroke’s immune dynamics, showing strong positive and negative correlations with macrophages and keratinocytes/neurons, respectively." (PMID 39595569, 2024). "Moreover, it prevented us from demonstrating that combining PRDX1 and GST-π levels results in better assessment of time of stroke onset even though a biomarker panel would be the best strategy to improve diagnostic performance." (PMID 27924073, 2016). "PRDX1 levels were not different in the stroke patients treated with reperfusion therapies vs. not, for all samples (32 ± 5.1 vs. 50 ± 7.6 ng/mL, p = 0.19) and in each time window (data not shown)." (PMID 27924073, 2016).
esophageal squamous cell carcinoma (10 papers, 2013 to 2023). Esophageal squamous cell carcinoma (ESCC) is a type of esophageal carcinoma (EC) that can affect any part of the esophagus, but is usually located in the upper or middle third. "In addition, low expression of PRDX1 indicated the risk of tumor progression and correlated significantly with reduced survival in oral squamous cell carcinoma, cholangiocarcinoma, esophageal squamous cell carcinoma, and pancreatic adenocarcinoma." (PMID 30104402, 2018). "Previous study reported that PRDX1 was functionally involved in Akt/mTOR in esophageal squamous cell carcinoma." (PMID 29492195, 2018). "An anticancer agent, FK228, inhibits the growth of esophageal squamous cell cancer and induces apoptosis in part through Prdx1 activation." (PMID 24009050, 2013). "However, the effect and mechanism of Prdx1 on esophageal squamous cell carcinoma still need to be further explored." (PMID 32357862, 2020). "Some groups found that PRDX1 may promote tumor development but other groups identified the tumor suppression function in breast cancer and esophageal squamous cell carcinoma." (PMID 29492195, 2018). "Prdx1 was recently identified as a candidate esophageal squamous cell carcinoma (ESCC)-related TAA in a previous study using a proteomics approach." (PMID 24009050, 2013). "In esophageal squamous cell carcinoma (ESCC), Prdx1 silencing has been shown to inhibit cell proliferation and induce apoptosis, whereas Prdx1 overexpression produces growth-promoting effects." (PMID 38007535, 2023).
non-small cell lung carcinoma (8 papers, 2013 to 2024). A group of at least three distinct histological types of lung cancer, including non-small cell squamous cell carcinoma, adenocarcinoma, and large cell carcinoma. "PRDX1 knockdown leads to the inhibition of proliferation and increase of apoptosis in non-small cell lung cancer cells through the Wnt/β-catenin pathway." (PMID 37227568, 2023). "PRDX1 promotes cell proliferation by activating Wnt–β-catenin signalling and is an independent prognostic factor for disease recurrence and reduced survival in patients with non-small-cell lung carcinoma." (PMID 38213773, 2024). "PRDX1 protects against oxidative stress by removing hydrogen peroxide, peroxynitrite and organic hydroperoxides, and is known to be reduced by TXN, supporting the proposal that non-small cell carcinoma in lung utilizes increased TXN to maintain PRDX1 in the reduced, active state." (PMID 26569310, 2015). "Our findings are consistent with those of a previous study on non-small cell lung cancer (NSCLC) indicating that the expression of Prdx1 was not statistically significantly correlated with the expression of Nrf235." (PMID 35027562, 2022). "However, besides its intracellular functions as a member of the peroxidase family and a protein chaperone, PRDX1 can be secreted via a nonclassical secretory pathway by non-small cell lung cancer cells." (PMID 25024510, 2014).
bladder cancer (7 papers, 2013 to 2025). "The significantly elevated urinary concentrations of PRDX1 & 2 in bladder cancer patients compared to healthy individuals suggests that these are potential biomarkers and can be used for disease surveillance." (PMID 35812179, 2022). "The median concentration of urinary PRDX1 was 29.4 ng/ml and significant elevation of urinary PRDX1 was found in bladder cancer patients compared to urine from healthy controls (p<0.001)." (PMID 35812179, 2022). "Though the median concentration of urinary PRDX1 was higher in the urine sample of recurrent bladder cancer patients compared to primary bladder cancer patients the difference was not statistically significant." (PMID 35812179, 2022). "Up-regulated level of PRDX1 was found in lung ovarian, liver, breast, gallbladder, prostate, and bladder cancer." (PMID 33053689, 2020). "PRDX1 and 2 both act as diagnostic markers, but it is PRDX2 which is significantly increased in recurrence and can be used as a urinary surveillance marker in bladder cancer patients." (PMID 35812179, 2022). "A significant elevation of urinary PRDX1 and PRDX2 concentration was found in bladder cancer patients and recurrent cases compared to the urine of healthy controls and primary bladder cancer patients (p<0.001 & p<0.01) respectively." (PMID 35812179, 2022). "The T-24 (urinary bladder carcinoma) cell line was completely negative to the anti-Prdx1 antibody." (PMID 24009050, 2013). "Unlike PRDX1, significant elevation of urinary PRDX2 was found in recurrent bladder cancer patients compared to primary bladder cancer patients (p=0.003)." (PMID 35812179, 2022).
colon cancer (7 papers, 2016 to 2025). "In a notable colon cancer study, PRDX1 was identified as a target of Celastrol, a promising natural product with antitumor properties." (PMID 40825764, 2025). "PRDX1 overexpression and PRDX6 under-expression were also shown in the stem-like colonospheres from colon cancer cells." (PMID 32231717, 2020). "Dy-regulations of the PRDX1 and PRDX6 were also confirmed in the stem-like colonospheres from colon cancer cells." (PMID 32231717, 2020).